KLK6 (kallikrein related peptidase 6)
Diseases named in the same sentence as KLK6 in open-access papers (continued):
Sharing a sentence is not in itself a finding about the gene and the disease.
tumor (continued). "KLK6 is a trypsin-like enzyme that can degade in vitro laminin and fibronectin, as well as other basic constituents of the extracellular matrix (ECM) and the basement membrane, and could be linked to tumour cell growth and malignant transformation." (PMID 17242704, 2007). "To validate this, we performed double immunofluorescence staining to assess the expression and localization of KLK6+EPC in 30 LCC and 40 RCC tumor tissue samples." (PMID 40932351, 2026). "KLK6, PRSS22, and PRSS3 are all secreted serine proteases, the first two identify CC tumor cells that are useful as tumor markers because they identify aggressive tumor cells." (PMID 40909962, 2025). "Overall, the β-catenin staining in tumor samples of CPC;Apcfl/fl;Klk6+/+ mice had the higher intensity score (average score of three) compared to the intensity of β-catenin staining in the tumors of CPC;Apcfl/fl;Klk6fl/fl mice (average score of two)." (PMID 39594797, 2024). "These genes include three tumour suppressors (DMBT1, MTUS1, and KLRC1), two genes involved with cell communication and myelin (GJB1 and KLK6), and a P450 monooxygenase involved in the synthesis of cholesterol and lipids (CYP4F12)." (PMID 37628980, 2023). "The novelty of the current study lies in the fact that we tried to modulate the genes KLK2, KLK4, KLK6, and KLK14 to inhibit the progression of PCa via miR-378, which can be produced in tumor cells through EPA, stimulating co-expression of the gene PGC-1β." (PMID 35681793, 2022). "The introduction of recombinant KLK6 protein in KLK6−/− mice rescued the production of TNF-α and CXCL1, tumor growth, and metastasis." (PMID 36552865, 2022). "In line with this, our results showed that the PAR1 inhibitor suppressed TNF-α and CXCL1 production and rKLK6-promoted tumor growth and metastasis in the xenograft model, suggesting that PAR1 plays a critical role in KLK6-mediated malignant progression." (PMID 36552865, 2022). "Because our results established that KLK6/PAR1 signaling mediates the crosstalk between macrophages and cancer cells, we assessed the effect of PAR1 on KLK6-mediated tumor growth in vivo." (PMID 36552865, 2022). "However, the function of KLK6 in the tumor microenvironment remains unclear." (PMID 36552865, 2022). "To assess the effects of KLK6 on tumor metastasis, we injected B16F10 or LLC cancer cells into WT and KLK6−/− mice via the tail vein." (PMID 36552865, 2022). "The localised KLK6 expression in tumour cells (identified by KRT19) and macrophages (represented by CD68) in the invasive areas underscores the potential for KLK6-targeted inhibitors that interfere with tumour-biological events in a context-dependent manner." (PMID 34439122, 2021). "We investigated the impact of LN tissue volume examined for detection of tumor cells using CEACAM5 mRNA levels as a proxy for tumor cell amounts, and KLK6 and SLC35D3 mRNAs as proxies for tumor cell aggressiveness." (PMID 34192710, 2021). "It has been reported that KLK6 and KLK7 cleave E-cadherin to promote tumour cell functions, including cell proliferation, migration and invasion." (PMID 34439122, 2021). "Comparison of the staining intensity between KLK6 and HMGA2 demonstrated a Spearman correlation of 0.70 (p < 0.001) with significant positivity in tumor (0.91, p < 0.01) and adjacent (0.81, p = 0.003) tissues." (PMID 31692974, 2019). "In the analyzed subset of clinical samples, a positive correlation between KLK6 and HMGA2 was found in the tumor samples and adjacent tissues (Spearman correlation coefficient is 0.91, p < 0.01, and 0.81, p = 0.03, respectively)." (PMID 31692974, 2019).
tumor (continued). "paratuberculosis as well as tumor markers such as thymidine kinase 1, Human epidermal growth factor family receptor-2/Neu (HER2) and telomerase, kallikrein 6 (KLK6), cancer antigen 15-3 (CA 15-3), and KLK3." (PMID 29043661, 2018). "We overexpressed KLK6 in AGS cells and injected mice with a tumor cell load of 1 × 107 cells to form a xenograft." (PMID 27863404, 2016). "For instance, kallikrein genes KLK5, KLK6 and KLK7 were downregulated in HPV16+ tumours and co-expressed with two overlapping antisense transcripts: CTB-147C22.8 and CTB147C22-9, as well as KLK10 with its antisense CTC-518B2.12." (PMID 29263803, 2016). "The spatial co-localization of KLK6-positive cells with SELENOP+ and SPP1+ macrophages is also particularly noteworthy, as these subsets are known to exhibit immunosuppressive properties and promote tumor angiogenesis." (PMID 41383634, 2025). "Comparing the bulk transcriptome profiles of the TD and nonTD patients, the TD patients exhibited upregulation of keratins (KRT81, KRT6B, KRT15, KRT5) and kallikreins (KLK5, KLK6, KLK7), indicating active extracellular matrix (ECM) remodeling and tumor expansion." (PMID 39664386, 2024). "The IHC analysis of KLK6 expression in the tumor tissue samples of ApcMin/+ mice and KLK6 expressing CPC;Apcfl/fl mice (CPC;Apcfl/fl;Klk6+/+) confirmed a similar pattern of KLK6 protein localization in the luminal and epithelial areas of the tumors in both mouse models." (PMID 39594797, 2024). "KLK6 is a secreted serine protease, which promotes the production of TNF-α by macrophages through PAR1 in the TME to stimulate the production of CXCL1 in tumor cells, thereby promoting tumor growth and metastasis." (PMID 38363409, 2024). "The differential gene expression levels between the tumor and adjacent tissue indicated that the ROBO1, KLK6, LIMK2, KLK7, NLGN4X, MBP, and NEDD9 gene expression levels were higher in normal tissues than in tumors; however, EFNA1 was higher in the tumor than the normal ones." (PMID 38137332, 2023). "ROBO1, KLK6, LIMK2, KLK7, NLGN4X, MBP, and NEDD9 expression levels were significantly higher in normal tissues than in tumors, demonstrating the possibility of being a tumor suppressor gene." (PMID 38137332, 2023). "The median H-scores of KLK2, KLK4, KLK6, and KLK14 protein expression in the nuclei of normal cells were 9, 24, 12.5, and 14.5, respectively, as compared with the tumor cells (42, 73.5, 43.5, and 62, respectively); therefore, the p values were 0.0027, 0.0009, 0.0062, and 0.0009, respectively." (PMID 35681793, 2022). "However, this inhibitory effect was reduced in KLK6−/− mice, suggesting that macrophages are, at least partially, important for KLK6-mediated tumor growth." (PMID 36552865, 2022). "In our study, we identified elevated expression of KLK6 in PDAC, and targeting KLK6/PAR1 signalling may be a promising therapeutic strategy to slow down tumour growth." (PMID 34439122, 2021). "To investigate the tumour-biological role of KLK6 in PDAC, we performed functional assays and hydrogel-based tumour spheroids and tested the effect of our KLK6 inhibitor on mRNA expression, metabolic activity, cell proliferation, migration and protease secretion." (PMID 34439122, 2021). "Our preclinical tumour spheroid model may be applied to test the PAR1 antagonist and to decipher the role of the KLK6/PAR1 axis, or other PARs, in PDAC." (PMID 34439122, 2021). "To establish tumour spheroids, we set up 3D cultures with Capan2 and MiaPaCa2 cells grown embedded in PEG-based hydrogels of varying composition (without RGD motif, RGD-functionalised, PC17) for 14 days and treated them with the KLK6 inhibitor." (PMID 34439122, 2021). "Upon image quantification using QuPath, we found that the KLK6 mRNA levels were significantly upregulated in PDAC compared to normal pancreas tissues, with invasive tumour areas having significantly higher mRNA levels compared to noninvasive tumour areas." (PMID 34439122, 2021).
tumor (continued). "In the CRC patients, KLK6 protein levels were elevated in the non-cancerous distant and adjacent tissues, compared to their paired tumor tissues (p < 0.0001 and p = 0.0157, respectively)." (PMID 31692974, 2019). "As a consequence, inhibitors of DNA methyltransferases could be used as promising drugs to restore KLK6 expression in order to reverse the EMT program and prevent tumor cell plasticity and dissemination." (PMID 28671620, 2017). "Positive staining was mainly detected in supra-basal keratinocytes of normal mucosa, while a more heterogeneous staining pattern ranging from absent to high KLK6 protein levels in tumor cells was evident in tumor sections." (PMID 25990935, 2015). "However, neither FaDu cells with silenced KLK6 expression nor HeLa cells with ectopic overexpression exhibited obvious changes in SMAD2/3 phosphorylation, questioning a major impact of KLK6 on canonical TGF-β signaling, at least in mucosal tumor cells." (PMID 25990935, 2015). "We obtained plasma samples before and after surgery from 70 laryngeal SCC patients and found a nonsignificant decrease in KLK6 concentrations after surgery, implying that plasma KLK6 most likely originates from tumor cells." (PMID 24669031, 2014). "The aim of this study was to determine the prognostic significance of kallikrein-related peptidase 6 (KLK6) and kallikrein-related peptidase 13 (KLK13) in epithelial ovarian cancer by quantifying gene expression levels with tumour pathology and patient survival data." (PMID 19707197, 2009). "Immunohistochemistry in native tumour tissue could prove not only an intense expression for KLK10 in 64.4% of the malignant cells, but also for KLK6 in 91.5%." (PMID 18854834, 2008). "Both benign ovarian tissues (median: 0.09; range: 0.01–16 ng mg−1) and nonovarian tumours that metastasised to the ovary (median: 0.09; range: 0.01–8.56 ng mg−1) also had relatively low KLK6 expression." (PMID 17242704, 2007). "KLK6 was strongly positive in normal breast tissue, but was not expressed in nine out of 14 tumour tissues, lower than normal in three and compared to normal in two (data not shown)." (PMID 14710225, 2004). "CNV score analysis revealed that Malignant, CASC15+KLK6+EPC, and UBD+S100A11+EPC exhibited significantly higher CNV scores than other subpopulations, indicating that these cells have a higher malignant potential and may play a key role in tumor progression." (PMID 40932351, 2026). "KLK6 was highly expressed by PDAC cells independent of tumour stage." (PMID 34439122, 2021). "As new immunotherapies and targeted therapies are revealed, our findings suggest value in further investigations into a panel of personalized tumor markers, which may include proteins with therapeutic relevance such as FOLR1, KRT19, KLK6, PARP-1, TROP2, and IFNL1." (PMID 34868557, 2021). "Moreover, while KLK6 and SLC35D3 were CC-tumor specific in the sense that only CC tumor tissue expressed the biomarkers compared to normal colon tissue or normal colon epithelial cells, CEACAM5 and MUC2 were expressed at approximately the same levels in normal and cancerous colon tissues." (PMID 32049988, 2020). "This suggests that KLK6 does not contribute to cell proliferation in the Apc-mutant intestinal tract but may influence tumorigenesis via different molecular pathways that influence the tumor microenvironment." (PMID 39594797, 2024). "However, KLK6 expression has not been observed in the urinary bladder, reflecting that KLK6 may be a tumor-related gene accompanied by the progression of BLCA." (PMID 36193495, 2022). "Although KLK6 expression was not correlated with tumour stage in our patient cohort, our findings suggest that a KLK6-targeted therapeutic intervention might be beneficial at the earlier tumour stage prior to the development of an invasive tumour area." (PMID 34439122, 2021). "The high levels of KLK6 protein were also detected in the ascites of CRC patients with peritoneal metastasis, but not in benign ascites." (PMID 35883559, 2022).
tumor (continued). "While the tumour-biological role of KLK10 in PDAC was assessed by gene silencing and a cell migration assay, the role of KLK6 was not further investigated." (PMID 34439122, 2021). "Coexpression of KLK6 with KRT19, αSMA or CD68 was independent of tumour stage, while KLK6 was coexpressed with KRT19 and CD68 in the invasive tumour area." (PMID 34439122, 2021). "KLK6, KLK7 and KLK 9 were abundant in the conditioned medium from ascites derived tumor cells, OVCAR3 and CaOV3, but not in ES2 cell conditioned media." (PMID 18560578, 2008). "In multivariate Cox regression models adjusted for tumour grade, histotype, CA125 and patient age, the relationship between KLK6 expression and patient survival was no longer significant." (PMID 17242704, 2007). "While KLK6-expressing stromal cells were not correlated with (non)invasive tumour areas and tumour stage, KLK6-expressing CD68+ cells were present in invasive tumour areas but not in noninvasive tumour areas and did not correlate with tumour stage." (PMID 34439122, 2021). "Additionally, the surviving tumour-free animals of groups KLK5/6, KLK5/10, and KLK6/10 did not display any detectable levels of kallikreins in the plasma for the duration of the study." (PMID 22102857, 2011). "Parental (KLK6 nonexpressing), C5 (KLK6 highly overexpressing), and C28 (KLK6 physiological‐expressing) MDA‐MD‐231 cells were selected for proteomic profiling to identify molecular pathways that determine their distinct tumor characteristics in relation to KLK6 levels." (PMID 30980596, 2019).
cancer (59 papers, 2002 to 2026). A tumor composed of atypical neoplastic, often pleomorphic cells that invade other tissues. "In the intrinsic view, KLK6-positive cells showed increased proximity to cancer-associated fibroblasts (myCAF, iCAF), plasma cells, SELENOP+ macrophages, SPP1+ macrophages, MK167+ macrophages, and endothelial cells." (PMID 41383634, 2025). "Here, we uncovered the mechanism underlying KLK6-mediated cross-talk between cancer cells and macrophages." (PMID 36552865, 2022). "KLK6 and 7 have been implicated in cancer angiogenesis and metastasis by its proteolytic effects cleaving fibrinogen, collagen and laminin." (PMID 29707153, 2018). "The serine protease KLK6, participates in diverse cancer-associated processes." (PMID 40168262, 2025). "KLK6 also triggers intracellular signaling by the activation of protease-activated receptors (PARs) that are implicated in various biological processes including inflammatory responses and cancer progression." (PMID 36552865, 2022). "So far, our in vitro data provide experimental evidence that loss of KLK6 expression supports proliferation, motility and treatment resistance of cancer cells originating from mucosal epithelia, which is-at least in part-due to the induction of an EMT-like phenotype." (PMID 25990935, 2015). "This may also hold true for advanced ovarian cancers, as we show high KLK6 expression is associated with later stage, more invasive, cancers." (PMID 19707197, 2009). "Serum levels of KLK6 in ovarian and invasive BrCa patients were significantly higher than in non-cancer controls." (PMID 41597241, 2026). "Klk6, a member of the family of secreted serine proteinases has been identified as an important player in different cancers and in inflammation response." (PMID 39924344, 2025). "Serum levels of KLK6 in ovarian and invasive BrCa patients were significantly higher than non-cancer controls." (PMID 41509368, 2025). "Activated KLK6 enzyme hydrolyzes extracellular matrix proteins, such as collagen, fibronectin, laminin, and fibrinogen, thus facilitating cancer cell invasion." (PMID 39594797, 2024). "KLK6 overexpression has been reported in various human cancers, including glioma, ovarian, gastric, skin, urinary bladder, and salivary gland tumors." (PMID 39594797, 2024). "Developing probes to detect specific KLK6 activity would facilitate further investigation into the specific roles of KLK6 functionality in cancer progression and help to validate KLK6 as a potential drug target." (PMID 39594797, 2024). "KLK6 can also enhance cancer cell proliferation through the cleavage and activation of protease-activated receptor 2 (PAR-2)." (PMID 39594797, 2024). "We treated with the CM of the control or that of RAW 264.7 cells transfected with the two KLK6 siRNAs into cancer cells." (PMID 36552865, 2022). "Numerous studies have evaluated KLK6 as a promising biomarker for early cancer diagnosis or unfavorable prognosis." (PMID 35883559, 2022). "Kallikrein-related peptidase 6 (KLK6) has been substantiated as a diagnostic, prognostic, and therapeutic molecular in several cancer types." (PMID 36193495, 2022). "Numerous metastatic lung nodules were observed in WT mice injected with B16F10 or LLC cells, whereas a considerably lower number of nodules was detected in KLK6−/− mice injected with cancer cells." (PMID 36552865, 2022). "Although aberrant expression of KLK6 was reported in several human cancers, the mechanism whereby the KLK6 gene is switched on is still poorly understood and is likely to be influenced by multiple mechanisms." (PMID 35883559, 2022). "The influence of KLK6 on cancer cell behavior was demonstrated through the silencing of KLK6 which resulted in a decrease in colony formation, an increase in cell adhesion to ECM, and inhibition of spheroid formation." (PMID 35883559, 2022). "Strong KLK6 staining was clearly seen in the mild dysplastic colonic mucosa and increased in intensity was observed as the dysplasia progressed to cancer." (PMID 35883559, 2022).